CAT (catalase)
Diseases named in the same sentence as CAT in open-access papers (continued):
Sharing a sentence is not in itself a finding about the gene and the disease.
cancer (continued). "Thus, the use of antioxidant enzymes such as catalase and superoxide dismutase may play a major role in inhibiting ROS formation, which can prevent cancer progression by removing and inactivating reactive oxygen species." (PMID 33976938, 2021). "Our study may provide valuable information to figure out the importance of LAW in the treatment of the cancer cells through inhibition of catalase, due to high concentration of ROS such as H2O2that could be a therapeutic alternative for the treatment of cancer." (PMID 32922495, 2020). "In tumor cells, inhibition of the activity of enzymes that neutralize oxidative stress e.g., catalase and superoxide dismutase, is observed, therefore the pro-oxidative potential of ascorbate is considered in the context of cells with impaired metabolism, e.g., cancer cells." (PMID 32455696, 2020). "Therefore, the combination therapy of CAT@liposome+H2O2@liposome could significantly enhance the therapeutic effect of cancer radiotherapy." (PMID 33343807, 2020). "The administration of A. zerumbet increased the CAT levels, which along with the restoration of lipid peroxide contents to near normal level indicate the anti-oxidant and free radical scavenging property of A. zerumbet and its potential use as anti-cancer agent." (PMID 31288458, 2019). "Therefore, these correlations between experiments suggest that 63 T at a concentration of 1 μM, particularly in cancer cells, may increase activity of CAT and GPx in response to overproduction of H2O2." (PMID 30498945, 2019). "Importantly, the authors also found that the present CAT could timely eliminate the appeared H2O2 as well as lowered the systemic toxicity of GOx-mediated cancer starvation therapy." (PMID 31754379, 2019). "Importantly, while mitochondria-targeted antioxidant ameliorates muscle loss and mitochondrial dysfunction of skeletal muscle in ageing rats, targeted overexpression of mitochondrial catalase protects against cancer chemotherapy-induced skeletal muscle atrophy and dysfunction." (PMID 29855350, 2018). "In contrast, SpCAT is activated by NaSH in MDST8 cancer cells, indicating that the inhibition of CAT in this cell line may solely occur through the generation of a temporarily inactive state of the enzyme, that is, CAT–Fe(IV)=O." (PMID 27848965, 2016). "It was demonstrated that ROS can induce autophagy through several distinct mechanisms involving Atg4-Atg8/LC3, Beclin-1, PI3K-Akt-mTOR, catalase, and the mitochondrial electron transport chain, which leads to both cell-survival and cell-death responses and could be selective toward cancer cells." (PMID 25891311, 2015). "Indeed, there are a number of reports of low catalase activity in various cancer cell lines." (PMID 25279352, 2014). "It has been reported that cancer cells have higher ROS content compared to normal cells probably due to abnormal respiration because of dysfunctional mutations in mitochondria, but they also have increased contents of antioxidants (SOD, catalase, glutathione, thioredoxin, etc.)to counteract ROS." (PMID 24648844, 2014). "The investigation demonstrated that the activities of both catalase and SOD were markedly diminished in the cancer cohort relative to the control cohort (p < 0.0001)." (PMID 41596358, 2026). "While CAT-tail modification of mitochondrial proteins due to compromised RQC has been noted in HeLa cells, the mechanistic involvement of RQC factors in cancer biology remains largely unexplored." (PMID 38798583, 2026). "As a result, according to the findings obtained, IMA and MDA levels decreased in the A549 cancer cell line, while GSH levels and SOD and CAT activity increased." (PMID 39945813, 2025). "Recently, several novel cascade nanoimmunomodulators, such as CMZM and IMZF, which possess multi-enzymatic activities including SOD, CAT, POD, and OXD, have been proposed to enhance cancer immunotherapy." (PMID 40072370, 2025).
cancer (continued). "Upon internalization by cancer cells, Fe/SAE@A triggered H2S-mediated inactivation of TrxR and CAT, thereby elevating intracellular H2O2 levels and initiating a potent ROS storm in GL261 cells, ultimately leading to irreversible LPO." (PMID 40838212, 2025). "Peroxidase-mimetic nanozymes are known to be effective in oxygen-dependent cancer phototherapeutics, including PDT, while catalase-mimetic nanosystems provide an additional source of molecular oxygen for the ROS production." (PMID 40871005, 2025). "Relying on its catalase function, the nanozyme generated O2 molecules from H2O2 for further photodynamic therapy of cancer cells." (PMID 40666180, 2025). "Therefore, CAT could serve as a prognostic marker and a therapeutic target in cancer treatment." (PMID 40424719, 2025). "CAT decomposes H2O2 into H2O and O2 and is often overexpressed in certain cancers, particularly acute myeloid leukemia." (PMID 40424719, 2025). "Catalase (CAT) facilitates the breakdown of hydrogen peroxide into water and oxygen, exhibiting anti-cancer and antioxidant properties." (PMID 41149930, 2025). "Simultaneously, catalase converted endogenous hydrogen peroxide into oxygen, increasing PDT efficiency and promoting cancer cell apoptosis." (PMID 40787898, 2025). "Low catalase expression correlates with high H2O2 production, influencing signalling pathway activation to induce proliferation, migration, and invasion in cancer cells." (PMID 38748263, 2024). "Moreover, alterations in CAT levels may impact the oxidative stress levels within cancer cells." (PMID 38540964, 2024). "Lower catalase activity may cause an escalated accumulation of reactive oxygen species (ROS) within leukemic cells, which in turn promotes antitumor signals such as cell death or susceptibility to apoptosis in CLL, thus accounting for a less aggressive behavior of cancer cells." (PMID 39540258, 2024). "Given that reduced CAT activity can lead to elevated physiological levels of H2O2, potentially activating signaling pathways that drive cancer cell metabolism and proliferation, these findings are not entirely surprising." (PMID 39594482, 2024). "Finally, they observed that CAT overexpression protects cancer cells against the pro-oxidant combination of ascorbate and menadione, suggesting that changes in the expression of antioxidant enzymes could be a mechanism of resistance of cancer cells toward redox-based chemotherapeutic drugs." (PMID 38891864, 2024). "They propose that the DNA breakage observed in cancer cells treated with LO is probably due to oxidative stress promoted by H2O2, since the pre-incubation with catalase partially prevented the cell growth inhibition effect promoted by LO." (PMID 38355518, 2024). "In contrast, chemoresistant cancer cells have antioxidant mechanisms (glutathione, SOD, catalase, and others) that are up-regulated, protecting them from ROS." (PMID 37446202, 2023). "Other worth-mentioning genes and metabolites previously reported in cancer progression are ASS1, CAT, ALDH7A1, arginine, glutamine, BCAAs, and AAAs." (PMID 37999208, 2023). "CAT and GSTP1 genetic variability was thoroughly studied in oxidative-stress-related diseases, especially different types of cancer, while in neurodegeneration, NFE2L2 and KEAP1 have recently gained the interest of researchers." (PMID 36829875, 2023). "Additionally, if the higher levels of catalase help to stabilize the radicals generated by cancer cells, this effect may be probably related to the greater mitochondrial dysfunction in K562 cells, caused by the co-treatment between Dox + EA-Aa, especially at the higher concentrations tested." (PMID 37654604, 2023). "Meanwhile, the cancer control group (MTC) exhibited less activity and CAT formation than the other groups." (PMID 37373429, 2023).
cancer (continued). "The treatment of dark tea can also effectively prevent cancer by increasing the activity of the antioxidant enzymes SOD, CAT, and GSH-Px, removing ROS produced by cells, and decreasing the level of MDA." (PMID 37764687, 2023). "The present results have shown significant up-regulation of SOD, CAT, and GPX in homogenized colon tissue in OME-treated rats (D and E) compared to those of the cancer controls." (PMID 36826002, 2023). "Cancer is a disease that itself produces oxidative stress and also decreases the enzymatic activity of antioxidant systems such as GPX, SOD, CAT, and non enzymatic molecules, such as vitamin C and E, among others." (PMID 36830015, 2023). "Although these functions make CAT and CDH1 intriguing examples of genes that have potentially evolved to enhance bat cancer resistance, previous studies have also found a signal for selection in CAT and CDH1 in other mammals." (PMID 37728212, 2023). "The levels of antioxidant enzymes, such as CAT (catalase) and SOD (superoxide dismutase), decrease in the presence of tumors since cancer cells generate a large amount of hydrogen peroxide." (PMID 37376098, 2023). "The second subnetwork containing 13 nodes and 12 edges showed the interaction between PRDX2 and TAGLN2 as well as a mild increase in multiple components of the peroxisome (SOD1, CAT, PRDX5, PRDX1) and proteoglycans in cancer (FLNA, STAT3)." (PMID 38322285, 2023). "For basal-like cancer, the highest content of toxic products of lipid peroxidation, in particular MDA, was noted against the background of minimal catalase activity." (PMID 35877435, 2022). "CAT can promote the decomposition of H2O2 to produce ROS, which highly improves the concentration of ROS in cancer cells." (PMID 35123493, 2022). "Specifically, the crucial antioxidant enzyme catalase (CAT), which decomposes H2O2 to O2 and H2O, is often altered in cancer cells." (PMID 36112236, 2022). "Both aKG and 5-HMF are also involved in increasing SOD, GPx and CAT to reduce RONS in cell culture and cancer patients." (PMID 36012295, 2022). "Catalase plays a crucial role in removing the H2O2, so when the catalase within the cancer cells is deactivated or expressed in lower numbers, the cancer cells are significantly more sensitive to oxidative stress." (PMID 35794980, 2022). "KMP has been shown to inhibit XO activity and increases the activities of catalase, HO, and SOD in a wide range of cancer and non‐cancer cells." (PMID 36259115, 2022). "Due to the high levels of ROS, cancer cells also stimulate the antioxidant system, which includes the enzymes superoxide dismutase (SOD), catalase (CAT), and glutathione peroxidase (GPX), to eliminate ROS." (PMID 36035213, 2022). "A newly presented meta-analysis correlated antioxidative activating enzymes, such as SOD, CAT, GPx and levels of RONS markers, namely, malondialdehyde (MDA) and 8-hydroxy-desoxoguanosine (8-OHdG), between cancer patients and a healthy population." (PMID 36012295, 2022). "Furthermore, hypoxia, the hard nut to crack facing cancer therapy, is simultaneously conquered, for the incorporated Pd nanoparticles located on TiO2 substrates during the black TiO2 construction play the role of catalase which can turn the nanoplatform into an oxygen manufactory." (PMID 35413839, 2022). "The rGCP nanogel was fabricated by copolymerizing two monomers, porphyrin, and cancer cells-targeted, Arg-Gly-Asp (RGD), onto the glucose oxidase (GOX) and catalase (CAT) surfaces." (PMID 35562969, 2022). "PtNPs were also proposed to be a catalase (CAT) mimicker and have been used to enhance radiation efficacy in the treatment of cancer." (PMID 35624849, 2022). "More interestingly, the Pt nanoenzyme mimicking CAT over the Sm-TCPP nanosheet effectively changed H2O2, overexpressed in the cancer microenvironment, into O2, thus alleviated cancer hypoxia." (PMID 35910842, 2022).
cancer (continued). "Levels of MDA, and P. carbonyl and MPO activity increased significantly in the cancer group (HCC) and were accompanied by a decrease in the activity of CAT and SOD enzymes." (PMID 35177980, 2021). "Various studies have reported the role of ROS in cancer, manifested by an increase in TBARS and PC and a reduction in the activity of SOD, GSH, and catalase." (PMID 34869321, 2021). "In this study we also did the antioxidant evaluation of plants by SOD, catalase and GSH, as oxidative stress is a primary marker for cancer." (PMID 33773549, 2021). "In this bioreactor, GOx and catalase (CAT) were embedded into PCN-224, followed by cancer cell membrane coating." (PMID 34993235, 2021). "So, the other method is to use catalase-mimic nanozymes to increase local oxygen concentration and indirectly improve the efficiency of radiotherapy and PDT to cancer tissues." (PMID 34423042, 2021). "The Pt NPs with CAT-mimicking capacity and Ru–Te hollow nanorods with OXD, POD-, CAT- and SOD-type activity both acted as carriers and relieved TME hypoxia to enhance cancer PDT/PTT effect." (PMID 34241715, 2021). "Therefore, to evade ROS-induced cell death, cancer cells have an aberrant metabolism that promotes some agents to scavenge ROS and repair ROS-induced damage with molecules like glutathione peroxidase, glutathione-S-transferase, glutaredoxin, thioredoxin, superoxide dismutase, and catalase." (PMID 33959633, 2021). "Based on studies of other cancers, it has been suggested that cells with low SOD and CAT activity profile and with variable GSH-Px activity promote cancer tumor formation." (PMID 34239688, 2021). "Superoxide dismutase- (SOD), catalase- (CAT), and glutathione (GSH)-related compounds are involved in the enzymatic disease control of cancer-suppressing reactions, glutathione peroxidase (GPx), glutathione reductase (GR), and thioredoxin reductase (TR)." (PMID 34770980, 2021). "Two ROS scavengers (CAT and NAC) were used to evaluate the changes in the anti-cancer effect of partial removal of ROS." (PMID 34641863, 2021). "The intracellular H2S does not only exhibit certain cytotoxicity, but also suppresses the expression of CAT which blocks the transformation pathway from H2O2 to oxygen, favoring the hypoxia condition in cancer cells." (PMID 32685012, 2020). "In this catalase-dependent self-perpetuation of singlet oxygen, the effect of CAP is also predicted to go beyond the surface of the cancer tumor." (PMID 33096638, 2020). "In our study we also did the antioxidant evaluation of plants by SOD, catalase and GSH, as oxidative stress is a primary marker for cancer." (PMID 33112576, 2020). "Other potential mechanisms leading to CAP selectivity on cancer cells include characteristic expression of NOX1, catalase and SOD in advanced malignant cells that require catalase deactivation prior to RONS-induced lipid peroxidation." (PMID 33202842, 2020). "The results showed that the inhibition induced by AsA on cancer cell growth was diminished by ROS scavengers, such as glutathione (GSH), catalase and superoxide dismutase (SOD), except for N-acetyl-L-cysteine (NAC)." (PMID 32992455, 2020). "Up-regulation of antioxidant enzymes (SOD, CAT, and glutathione S-transferase) resulted from L. plantarum AS1 in the colon of cancer-bearing subjects suggests an anticancer benefit of this probiotic through its antioxidant attributes." (PMID 33392276, 2020). "A higher lipid peroxidation and disturbed antioxidant enzyme activities (superoxide dismutase (SOD), catalase (CAT), glutathione peroxidase (GPx) as well as glutathione (GSH) are generally detected in cancer patients." (PMID 32986349, 2020). "Of note, HAAO, MGLL, and UPGE were down-regulated in 18 cancer types; ADHFE1, CAT, and MSRA were down-regulated in 19; and RGN was down-regulated in 21 different types of cancer." (PMID 31351478, 2019).
cancer (continued). "The antioxidant gene CAT was upregulated, along with PLCD1, which is involved in immune signal transduction and plays a role in cancer suppression." (PMID 31569385, 2019). "Several studies have shown that miRNAs can upregulate cellular ROS levels in cancer cells by inhibiting antioxidants including SOD and catalase." (PMID 31717786, 2019). "Cancerous tissues generate oxidative stress and this was measured using antioxidant parameters including TBARs, SOD, catalase, GSH and PC." (PMID 35541235, 2018). "To verify that the anti-cancer effect of GC/AscH− treatment is H2O2-dependent, we utilized an H1299T cell line that conditionally overexpresses catalase when exposed to doxycycline (H1299T-CAT)." (PMID 29351198, 2018). "Addition of catalase, an enzyme that specifically degrades hydrogen peroxide (H2O2), completely reversed ascorbate-induced cell death in cancer cells." (PMID 29215048, 2017). "ROS accumulation in cancer cells induces expression of PGC-1å/ß to promote detoxification through direct induction of superoxide dismutase 2 (SOD2), catalase and glutathione peroxidase." (PMID 29100366, 2017). "Of the antioxidant enzymes, manganese superoxide dismutase (MnSOD), catalase (CAT) and sestrin 3 (SESN3) are reported to play important roles in ROS detoxication in cancer cells." (PMID 29152111, 2017). "In the present study, decreased activities of antioxidant enzymes, such as SOD, CAT, GPx, GST and GR, were observed in cancer-bearing rats, which indicates that DEN-induced oxidative stress leads to HCC." (PMID 27187346, 2016). "We recently developed Kochi Oxydol-Radiation Therapy for Unresectable Carcinomas (KORTUC) as a strategy to increase intratumoral oxygen concentrations and degrade antioxidant enzymes such as peroxidase and catalase." (PMID 26751477, 2016). "We recently developed Kochi Oxydol-Radiation Therapy for Unresectable Carcinomas (KORTUC) as a method to increase intratumoral oxygen concentrations and inactivate antioxidative enzymes such as peroxidase and catalase." (PMID 26751477, 2016). "It has been reported that a high level of H2O2 produced by increasing SOD activity or decreasing GPx and CAT activity leads to H2O2 accumulation and cancer cell death." (PMID 26700476, 2015). "In the presence of scavengers (CAT and NAP), ATP levels recovered significantly by 14% to 26% (p < 0.05) in cancer cells when compared to the plasma-treated group." (PMID 25715710, 2015). "CAT and NAP scavengers reduced the caspase activity by 161% to 209% (p < 0.01) in both cancer cells when compared to the plasma-treated group." (PMID 25715710, 2015). "Whereas in cancer cells which have lower activity of SOD and CAT than normal cells, ·O2− is kept at a higher level." (PMID 26330167, 2015). "In contrast, the presence of CAT and MAN scavengers increased the red fluorescence of JC-1 by 27% to 45% in cancer cells when compared to the plasma-treated group." (PMID 25715710, 2015). "The activity of antioxidant enzymes including superoxide dismutase (SOD), catalase (CAT) and glutathione peroxidase (GPx) are particularly important in cancer cell development and maintenance." (PMID 26700476, 2015). "Drugs bind to enzymes and elicit enzyme inhibition; one such example is catalase inhibition by wogonin led to H2O2 accumulation and cytotoxicity in cancer cells through H2O2-mediated NF-κB suppression and apoptosis activation." (PMID 25025898, 2014). "A recent study reported that CAT overexpression in MCF-7 cells led to less proliferation and migration of the cancer cells." (PMID 23153283, 2012). "This synergistic effect may be mediated by increased production of reactive oxygen species (ROS) and a weakening of the cancer cells' antioxidant defenses, including reductions in glutathione, GPX4, and catalase." (PMID 41972356, 2026).